RNU6-1104P (RNA, U6 small nuclear 1104, pseudogene)
Gene: Small nuclear RNA gene on chromosome 7 (101,269,938 to 101,270,041, reverse strand). Ensembl gene ENSG00000207454.
Homologues: Orthologues: chimpanzee U6 (99% identical), rabbit U6 (88% identical), rat LOC120093296 (84% identical), dog U6 (81% identical), mouse Gm23244 (77% identical). Paralogues in human: RNU6-16P (92% identical), RNU6-1 (91% identical), RNU6-15P (91% identical), RNU6-2 (91% identical), RNU6-393P (91% identical), RNU6-39P (91% identical), RNU6-3P (91% identical), RNU6-4P (91% identical), RNU6-5P (91% identical), RNU6-6P (91% identical), RNU6-9 (91% identical), RNU6-10P (90% identical), and 1288 more.